HMGXB4 (HMG-box containing 4)
Description:
Negatively regulates Wnt/beta-catenin signaling during development.
Synonyms: HMG2L1; HMGBCG; THC211630; P53N
Tractability: PROTAC: UniProt records ubiquitination sites on it; ubiquitination databases record sites on it; its protein half-life has been measured.
Gene: Protein-coding gene on chromosome 22 (35,257,452 to 35,295,807, forward strand). Ensembl gene ENSG00000100281.
Subcellular location: Nucleus
Subcellular location (Human Protein Atlas): Nucleoplasm
Gene Ontology:
Molecular function: identical protein binding; protein binding
Biological process: endosome to lysosome transport; negative regulation of Wnt signaling pathway
Cellular component: NURF complex; nucleus
Genetic constraint (gnomAD): Loss-of-function variants: 25 observed, 49.85 expected, observed/expected ratio (o/e) 0.5, 90% interval 0.36 to 0.7. The upper end of that interval is the gene's LOEUF score, 0.7, which puts it in group 2 of 6, group 1 being the genes least tolerant of losing a copy. Missense variants: 583 observed, 674.36 expected, observed/expected ratio (o/e) 0.86, 90% interval 0.81 to 0.93. Synonymous variants: 246 observed, 258.35 expected, observed/expected ratio (o/e) 0.95, 90% interval 0.86 to 1.06.
Homologues: Orthologues: chimpanzee HMGXB4 (99% identical), macaque HMGXB4 (97% identical), pig HMGXB4 (94% identical), dog HMGXB4 (94% identical), rabbit HMGXB4 (92% identical), mouse Hmgxb4 (87% identical), guinea pig HMGXB4 (86% identical), rat Hmgxb4 (86% identical), tropical clawed frog hmgxb4 (57% identical), zebrafish hmgxb4a (53% identical), Caenorhabditis elegans hmg-3 (8% identical), Caenorhabditis elegans hmg-4 (8% identical). Paralogues in human: UBTF (17% identical), TOX2 (15% identical), TOX (14% identical), TOX3 (13% identical), TOX4 (12% identical), SP100 (12% identical), SSRP1 (11% identical), UBTFL1 (9% identical), SMARCE1 (8% identical), SP140 (8% identical), HMGB1 (8% identical), SP110 (8% identical), and 8 more.
Diseases named in the same sentence as HMGXB4 in open-access papers:
HMGXB4 is named in the same sentence as 3 diseases in open-access papers, as found by Europe PMC text mining. Sharing a sentence is not in itself a finding about the gene and the disease. The quoted sentences say what the papers report.
endotoxemia (1 paper, 2024). "Recently, our study further revealed a critical role of HMGXB4 in exacerbating endotoxemia by promoting a systemic inflammatory response in mice." (PMID 38644513, 2024). "Our previous studies have demonstrated that HMGXB4 suppresses smooth muscle differentiation and exacerbates endotoxemia by promoting a systemic inflammatory response in mice." (PMID 38644513, 2024).
pancreatic cancer (1 paper, 2022). "A necroptosis-relevant risk model was developed for predicting pancreatic cancer survival and responses to immuno- and chemotherapy, comprising MYEOV, HDAC4, TLDC1, PITPNA, FNDC3B, HMGXB4, and BAX." (PMID 35662734, 2022). "BAX, FNDC3B, HDAC4, HMGXB4, MYEOV, and TLDC1 displayed upregulated expressions in pancreatic cancer than normal tissues." (PMID 35662734, 2022).
cancer (1 paper, 2023). A tumor composed of atypical neoplastic, often pleomorphic cells that invade other tissues. "Following this line, aberrant activation of HMGXB4 in differentiated cells (e.g., cancer) might result in undesirable transactivation of target gene expression." (PMID 37108449, 2023).